CD7 (CD7 molecule)
Diseases named in the same sentence as CD7 in open-access papers (continued):
Sharing a sentence is not in itself a finding about the gene and the disease.
acute myelomonocytic leukemia (1 paper, 2018). "One case of acute myelomonocytic leukemia (M4) showed expression of CD7 and CD64 along with cytogenetic abnormality del9 (q21-23.3)." (PMID 29805426, 2018).
AIDS (1 paper, 2017). A syndrome resulting from the acquired deficiency of cellular immunity caused by the human immunodeficiency virus (HIV). "PAP-based immunotoxins were used in the treatment of AIDS patients and some of them (e.g., TXU (anti-CD7)-PAP) reached clinical trials where they reduced the viral burden in all HIV-1-infected adult patients without any adverse reactions." (PMID 29104238, 2017).
chronic lymphocytic leukemia (1 paper, 2025). "In fact, several cases of lineage switch have been reported post-CAR therapy: chronic lymphocytic leukemia transforming into plasmablastic lymphoma, mantle cell lymphoma transforming into histiocytic sarcoma, and T-ALL transforming into AML after CD7 CAR-T treatment." (PMID 41487532, 2025).
coeliac disease (1 paper, 2009). "γδIELs, αβIELs, and CD2+CD7+IELs isolated from intestinal biopsies of children with active coeliac disease and treated coeliac disease were also analysed for expression levels of preTα mRNA." (PMID 18299319, 2009). "The preTα mRNA expression levels were significantly lower in the CD2+CD7+IELs of patients with coeliac disease, both in active and inactive disease, as compared to controls." (PMID 18299319, 2009).
cylindroma (1 paper, 2024). "On microscopical examination, the tumor exhibited histological and immunohistochemical characteristics of a rare breast cylindroma, namely, consisted of tightly packed cell islands of inner epithelial CD7+ and outer myoepithelial cells p63+ forming the typical “jigsaw”/“mosaic” pattern." (PMID 39439661, 2024).
deficiency anemia (1 paper, 2015). "CD56 was expressed in monocytes in 2 cases, CD7 and CD19 were expressed in one case each (cases with deficiency anemia)." (PMID 25924846, 2015).
eosinophilia (1 paper, 2025). "Bone marrow flow cytometry demonstrated eosinophilia and 3% atypical T-cells with an immunophenotype of CD3−, CD4+, CD2+, CD5+, CD7−, CD8−." (PMID 41488087, 2025).
epilepsy (1 paper, 2016). A brain disorder characterized by episodes of abnormally increased neuronal discharge resulting in transient episodes of sensory or motor neurological dysfunction, or psychic dysfunction. "CD7 (T cells + Natural Killer, NK) differ between vascular encephalopathy and psychosis, migraine, epilepsy, and mental retardation." (PMID 27190492, 2016).
hepatitis B (1 paper, 2022). "We report the case of one patient with hepatitis B associated with relapsed/refractory acute T-lymphocytic leukemia (T-ALL) treated with donor-derived CD7 CAR-T therapy and allogeneic hematopoietic stem cell transplantation." (PMID 35903089, 2022). "This is the first study on the safety and effectiveness of donor-derived CD7 CAR-T therapy bridging to allogeneic hematopoietic stem cell transplantation in a patient with relapsed/refractory acute T-lymphocytic leukemia and hepatitis B." (PMID 35903089, 2022).
hepatitis C (1 paper, 2015). "There was one case with an autoimmune disorder presenting expression of CD34 in maturing granulocytes without any other abnormality, and one with hepatitis C at diagnosis presenting expression of CD7 in maturing granulocytes." (PMID 25924846, 2015).
Hodgkins lymphoma (1 paper, 2022). A heterogeneous group of malignant lymphoid neoplasms of B-cell origin characterized histologically by the presence of Hodgkin and Reed-Sternberg (HRS) cells in the vast majority of cases. "On the contrary to CD7 or CD4, it is expressed only on a small subset of normal T-cells but it is expressed in various T-cell malignancies including Hodgkin’s lymphoma (HL), T-ALL, ALCL, AITL, and PTCL-NOS." (PMID 35600381, 2022).
inflammatory bowel disease (1 paper, 2021). A spectrum of small and large bowel inflammatory diseases of unknown etiology. "The prevalence of HP infection in patients with inflammatory bowel disease (IBD) is low, and both case–control and ecological studies clearly show an inverse correlation between the prevalence of HP infection and development of CD7." (PMID 34504159, 2021).
kidney cancer (1 paper, 2024). Primary or metastatic malignant neoplasm involving the kidney. "Several genes showed a low gDS in most kidney cancer cell lines, such as CD82, CD7, MEST, SELP, BMP6, CA2, DNAJC6, and VEPH1." (PMID 38728235, 2024).
lung carcinoma (1 paper, 2017). "By utilizing human NK cells (CD3−CD56+CD7+) as effectors, anti-CD47 antibody did not induce increased ADCC of lung cancer cell line cells or primary patients tumor cells compared to IgG1 isotype control." (PMID 28484448, 2017).
malaria (1 paper, 2025). Malaria is a serious and sometimes fatal disease caused by a parasite that commonly infects a certain type of mosquito which feeds on humans. "Recently, another CD56–, CD7+, FcRγ chain negative NK cell population was found to be associated with malaria exposure and protection from malaria, similar to CD56 dim (positive), FcRγ chain negative NK cells." (PMID 40337867, 2025).
metastatic cancer (1 paper, 2023). A carcinoma which has spread from the original site of growth to another anatomic site. "For the identification of the primary site of metastatic cancer, immunohistochemistry using CD7, CD20, and CDX2 has become a useful examination." (PMID 37872388, 2023).
Mycosis (1 paper, 2015). "Biopsy results demonstrated CD4 positivity, consistent with Mycosis Fungoides with coexpression of CD5, CD47, and CD7." (PMID 26380134, 2015).
myeloid leukemia (1 paper, 2019). A clonal proliferation of myeloid cells and their precursors in the bone marrow, peripheral blood, and spleen. "Several molecular targets expressed on myeloid leukemia cells, such as CD123 and CD33 but also NKG2DLs and CD7, are currently being explored in the CAR field and more efficient protocols for CAR-NK cell development are being established." (PMID 31681270, 2019).
neuroendocrine tumor (1 paper, 2008). "Immunohistochemistry revealed that this lesion was positive for synaptophysin and CD56, but negative for chromogranin as well as CD10, CD7, and CD20, consistent with a well-differentiated neuroendocrine tumor." (PMID 18430248, 2008).
non-small cell lung adenocarcinoma (1 paper, 2013). Type of epithelial lung cancer arising from glandular origin. "Immunohistochemistry result were negative for TTF-1, Thyroglobulin, CD7 and CD20 which ruled out non-small cell lung adenocarcinoma, thyroid cancer and gastrointestinal tract cancer respectively." (PMID 29147330, 2013).
pseudolymphoma (1 paper, 2025). A neoplastic process that resembles a malignant lymphoma, but has a benign course. "Our patient’s presentation - polymorphous infiltrate, modest CD7 reduction, CD4-predominant dermal infiltrate, negative TCR clonality, and recent HCTZ exposure supported the pseudolymphoma LDR diagnosis over MF." (PMID 41550319, 2025).
pulmonary lymphoma (1 paper, 2026). "Bronchoalveolar lavage (BAL) flow cytometry demonstrated an aberrant CD4-predominant T-cell population (CD4:CD8 ratio 9.2:1) with loss of pan-T cell antigens CD5 and CD7, providing early evidence of pulmonary lymphoma involvement and prompting expedited hematological evaluation." (PMID 42212304, 2026).
rheumatic diseases (1 paper, 2025). "As early as the 1990s, researchers realized that CD7 might contribute to the pathogenesis of rheumatic diseases, and the effect of monoclonal antibody to CD7 on rheumatic diseases was also evaluated in the clinical setting." (PMID 40761479, 2025).
T-cell deficiencies (1 paper, 2021). "The ability of transplanted CD7+ progenitors generated in the present culture system to treat T-cell deficiencies will be investigated in a forthcoming clinical trial (NCT03879876) that has been approved by the French Drug Agency." (PMID 34117371, 2021).
Thrombocytopenia (1 paper, 2021). A reduction in the number of circulating thrombocytes. "Compared with the non-leukemic ALK-negative ALCL group, patients with leukemic disease more often had absolute lymphocytosis (50% vs. 0%, p = 0.008), thrombocytopenia (60% vs. 11%, p = 0.03), bone marrow involvement (50% vs. 14%, p = 0.04), and CD7 positivity (71% vs. 19%, p = 0.02)." (PMID 34944936, 2021).
tumor (146 papers, 2007 to 2026). "An immunohistochemical analysis can further identify peculiar features of the tumor cells, such as the loss of CD7, low number of CD8+ infiltrates, and increased Ki67 expression." (PMID 39996780, 2025). "This may be caused by a significant reduction in tumor burden after receiving chemotherapy and before CD-7 CAR-T-cell infusion." (PMID 39620223, 2024). "Frameshift or missense mutations were detected in the four CD7-negative relapse patients, suggesting that mutations may be a main cause of CD7 loss in tumor cells." (PMID 37711206, 2023). "However, frequent loss of CD7 is observed in tumor cells of PTCL." (PMID 33292562, 2020). "Evaluation of peripheral blood one-week post-CD7-RTX CAR T treatment revealed partial remission (PR) with 97.29% reduction in tumor burden." (PMID 40821791, 2025). "The results showed that this treatment strategy can effectively alleviate the condition of 10 patients, providing a safe and effective treatment plan for CD7‐positive tumour patients." (PMID 40665579, 2025). "Taken together, K12 CAR-T cells had prominent cytotoxicity toward CD7-positive tumor cell lines and had increased CD7-restricted activation and prolonged cytotoxic activity compared to scFvCD7 CAR-T cells in vitro." (PMID 40589566, 2025). "The dVHH NS7CAR-T cells demonstrated enhanced antigen-binding specificity, affinity, and anti-tumor efficacy in xenograft mouse models compared to single nanobody- and scFv-based CD7 CAR-T cells in xenograft models." (PMID 40474230, 2025). "NK-92MI cells expressing either monovalent CD7 NbCAR or bivalent dCD7 NbCAR demonstrated consistent and potent cytotoxicity against both cell lines and primary tumor cells of T-ALL." (PMID 40474230, 2025). "K12 CAR-T cells generated from CD7KO T cells effectively eliminated CD7-positive tumor cell lines as well as T-ALL and CD7-positive AML-patient-derived samples in vitro." (PMID 40589566, 2025). "While flux, and thus tumor burden, continuously increased in control mice, it remained at approximately background levels for those treated with CD7-RTX CAR T cells." (PMID 40821791, 2025). "Twelve studies were on T cell malignancies; they KO CD2, CD3, CD5, or CD7 and simultaneously targeted these antigens on tumor cells." (PMID 41354926, 2025). "CD7-positive tumor cell lines exhibited similar properties as follows: Blocking the CD7 protein expression in CD7-positive cell lines reduced their metastatic capacity in the mouse model." (PMID 40564892, 2025). "While control mice were observed to have significant residual tumor burden in peripheral blood analysis, mice treated with CD7-RTX CAR T cells demonstrated remarkable >99% complete depletion." (PMID 40821791, 2025). "This reduction was observed in an E:T-ratio-dependent manner in various CD7-positive cell lines, but not the CD7-negative cell line U937, with a mean tumor cell lysis of 74.5% for Ramos.CD7, 69.3% for CEM, 77.8% for Hut78, and 64.0% for Molt-4." (PMID 40589566, 2025). "Further estimation indicated CD8+ T cell subsets including Tem, Tcm, γδ T cells, NK cells and Lin− CD7+ cells were enriched in iCMS3 tumours, whereas B/plasma cell and naïve T cells were enriched in iCMS2 tumours." (PMID 39934971, 2025). "Then, The patient remained in complete remission (CR) for four months before a relapse with 26.64% chimerism rate, so he was treated with allogeneic anti-CD7 CAR-T cells after chemotherapy reducing the tumor burden." (PMID 39877371, 2025). "Here, although we only emphasized the antitumor activity of J87-Dxd against T-ALL cells, it is likely that J87-Dxd remains effective against other CD7-positive tumor cells." (PMID 38254706, 2024). "All these data showed that long-lasting CAR-T cells after HSCT had a persistent killing ability of CD7-positive tumor cells and T cells contributing to prevention of leukemia relapse and GvHD." (PMID 39609714, 2024).
tumor (continued). "Although the relapse rate was 30%, four patients who relapsed lost CD7 expression in their tumor cells." (PMID 38915099, 2024). "Autologous CD7 CAR-T cells effectively removed tumor cells from patients in an open-label phase I clinical trial (NCT04004637)." (PMID 39609714, 2024). "Naturally selected CD7 CAR-T cell therapy has tumor-killing effects based on in vitro and AML xenotransplantation models, whereas, it has no cytotoxic effects on normal myeloid cells." (PMID 39469704, 2024). "Six patients experienced disease relapse with a median time-to-relapse of 6 (range, 4.0–10.9) months, and 4 of these 6 patients were found to have lost CD7 expression on tumor cells." (PMID 37020231, 2023). "Reduction of tumor burden indicated that CD7-CAR-T cell prevents systemic leukemia progression making them treatment for refractory or relapsed AML." (PMID 37803464, 2023). "Immunohistochemical staining of the tumor cells showed positivity for CD2, CD3, CD4, CD5, CD25 and CD45 and partial loss of CD7." (PMID 36975591, 2023). "Due to CD7 expression on T cells it is necessary to engineering CAR-T cells to avoid CD7 expression ad allow targeting of only tumor cells." (PMID 37803464, 2023). "The CD7 CARCD7- T-cells screened showed superior anti-tumor function and durability compared to conventional CAR T-cells, and a distinct transcriptional activation spectrum." (PMID 37215124, 2023). "Unexpectedly, the C8 population of cancer cells expressed T-cell markers (CD3D, CD3E, CD7), which is recognized as a dual identity of T cells and tumor cells involved in the role of the TME." (PMID 36451812, 2022). "Despite undergoing two rounds of antigen stimulation, Tan5-7, and Tan7-5 CAR-T cells maintained cytolytic stamina and showed significantly better lysis of CD7− tumor cells than Dual CAR-T cells." (PMID 35332132, 2022). "The results suggested that FHVH3 CAR-T cells had comparable cytolytic effects on CD7+ tumor cells with TH69 CAR-T cells." (PMID 35332132, 2022). "Researchers made CD5/CD7 CAR-T cells that showed anti-tumor substantial effects in malignant T cell lines such as Jurkat, CCRF-CEM, MOLT, and in xenogeneic mouse models established using CCRF-CEM-ffLuc cell injections." (PMID 36261831, 2022). "The ability of anti-CD7 CAR NK-92MI to specifically eradicate CD7-positive tumor cells was observed both in vitro and in T-ALL PDX mouse models." (PMID 36428748, 2022). "In the peripheral blood of SS patients, CD4+CD7− T cells, which were considered to be tumor cells, expressed both OX40 and OX40L, while CD4+ T cells in the peripheral blood of healthy subjects expressed OX40, but OX40L was weakly expressed." (PMID 34830466, 2021). "In the non–tumor-bearing mice, these results were statistically significant, despite the variability of T cell engraftment and the high percentage of CD7– T cells in mice with control HSCs." (PMID 34423790, 2021). "Quantifying these expression differences for tumor cells relative to reactive CD4+ T cells revealed fold-changes of 0.26 for CD7, 1.40 for CD30, 3.20 for CD25, and 5.73 for Ki-67." (PMID 34795254, 2021). "It is intriguing that mice with CD7-KO HSCs and tumor, followed by UCART7 treatment, had less detectable UCART7 expansion in the peripheral blood than mice with control HSCs." (PMID 34423790, 2021). "As previously reported, variation in expression of the CD3 and CD7 T-cell markers can be used to discriminate normal T cells (CD3 high/CD7+) from tumor T cells (CD3dim/CD7-)." (PMID 28881727, 2017). "For each biopsy, strong 5-hmc staining was found in residual normal T cells while poor signal was observed in the predominant population of CD7- tumor cells." (PMID 28881727, 2017). "That loss or dim expression of CD7 and CD26 can be found in patients with benign inflammatory dermatoses and aberrant dim CD3 can be observed in nonneoplastic T cells." (PMID 26788525, 2015).